AR (androgen receptor)
Diseases named in the same sentence as AR in open-access papers (continued):
Sharing a sentence is not in itself a finding about the gene and the disease.
tumor (continued). "Among the HR‐positive patients, significant differences in age, N stage, histological subtype, tumor‐infiltrating lymphocytes (TILs), androgen receptor (AR) status, TOPIIa, and surgical modality were found between the HER2‐low and HER2‐0 BC patient groups (p < 0.05)." (PMID 37772432, 2023). "Involvement of FOX family in PCa formation and metastasis has been reported in numerous cases, of which FOXA1 is essential in regulating AR-mediated tumor development, and other FOX members have been confirmed to play regulatory roles in progression of various cancers." (PMID 38057852, 2023). "AR expression was also correlated with survival in vitro and time to tumor progression in vivo." (PMID 37455903, 2023). "Blocking AR functions also exhibited significant efficacies of tumor growth suppression." (PMID 36594084, 2023). "In contrast, in ER-negative tumors, AR mostly binds to androgens, increasing tumor growth." (PMID 38067367, 2023). "This suggested that the inversion and the deletion were both contained on the same DNA molecule, and raised the possibility that co-occurrence of multiple AR gene rearrangements in a tumor reflects the presence of complex, multiply-rearranged AR gene structures." (PMID 37636316, 2023). "Therefore, the tumour metabolism is indirectly targeted by directly targeting the AR signalling during the therapy approach of metastasised PCa." (PMID 36151426, 2023). "A previous study demonstrated that the transcriptional programs regulated by AR could drive the tumor-infiltrating CD8 + T cell exhaustion in male cancer patients, contributing to the sex differences in antitumor immunity." (PMID 37696831, 2023). "However, the majority of CaP patients develop androgen independence via abnormal androgen receptor signaling, which promotes tumor growth." (PMID 37895357, 2023). "In addition, we examined the expression of AR in subcutaneous transplanted tumor of mice by immunohistochemistry." (PMID 37716981, 2023). "In addition, the anti-PD-L1 antibody treatment of mice implanted with Hep1-6-PCDH (AR-) or Hep1-6-AR (AR+) tumor cells resulted in smaller tumors in mice implanted with Hep1-6-PCDH (AR-) cells than in mice implanted with Hep1-6-AR (AR+) cells." (PMID 37373038, 2023). "Downstream and upstream effectors of AR are also found to be altered in primary tumor samples." (PMID 36937425, 2023). "In the xenografted tumor experiments, gefitinib was more effective in the absence of hormones, owing to the inverse correlation between AR signaling activity and EGFR signaling activity associated with HS3ST1 expression." (PMID 37463954, 2023). "The lack of expression of an active AR in these cell lines could provide an opportunity to ectopically over-express the different AR reported isoforms, improving our understanding of their roles in tumour initiation and development." (PMID 37264224, 2023). "CPT can exert its anti-tumor activity by inhibiting tumor cell migration and invasion, inducing tumor cell apoptosis, inhibiting the generation of new blood vessels, inhibiting tumor cell proliferation, regulating androgen receptor signaling, inhibiting lymphangiogenesis and so on38." (PMID 38129556, 2023). "Consequently, ADT can inhibit AR signaling, and predominantly inhibit the tumor-suppressive function of ERβ." (PMID 37361598, 2023). "In CRPC patients, the combination of androgen-receptor-axis-targeted therapies (ARATs) may lead to improved tumor control." (PMID 38264741, 2023). "Combination therapy did not improve efficacy, probably due to the high dose of olaparib, which, already greatly reduced tumor volume alone and because of the neuroendocrine nature of the C1022 tumor given that abiraterone and enzalutamide are efficient on AR+ tumors." (PMID 37305585, 2023). "Even in castrate-resistant prostate cancer (CRPC), the AR plays a major role in tumor growth." (PMID 37175938, 2023).
tumor (continued). "Further resistance to ARSI may result from tumor cells switching from AR-dependent to AR-independent signaling pathways." (PMID 36902032, 2023). "However, the extent of decline and interval it takes to get to the nadir level was variable 32, depending on the death of differentiated neoplastic cells and/or decrease in expression of androgen receptor (AR) stimulated PSA in surviving tumour cells 30,34." (PMID 37545899, 2023). "More importantly, they show that reducing RUNX1 transcriptional activity may be an opportunity to improve the sensitivity of CSC/CTC to chemotherapy leading to a potential reduction in metastasis or tumor recurrence in AR+-TNBC." (PMID 36766786, 2023). "Interestingly, as the LNCaP cells used contained an integrated AR luciferase reporter, in 3/10 mice we detected an additional luciferase signal emanating from outside the tumour—indicative of likely metastatic deposits." (PMID 37373067, 2023). "Furthermore, it has been shown that AR gene amplification is frequently detected in the circulating tumor cells (CTCs) of patients with CRPC." (PMID 36768370, 2023). "Importantly, in direct comparison, our compounds are more effective than enzalutamide and docetaxel in achieving tumor growth inhibition/repression in the AR+ MDA-MD-453 xenograft model in mice." (PMID 37766871, 2023). "Monitoring the serum PSA level provides insight into both the disease burden and the biology of the disease; however, some mCRPC patients may have a low PSA level, because the tumor is less dependent on androgen receptor signaling." (PMID 38264741, 2023). "CRPC onset may be due to androgen receptor gene mutations and amplification that causes a persistent androgen receptor signaling activation during ADT, enhancing tumor cells growth." (PMID 37296999, 2023). "Because cancer stem cells are capable of initiating tumor growth, the targeting of AR alongside chemotherapy may be a viable method for preventing recurrent disease." (PMID 37835396, 2023). "AR conditional expression in mouse urothelium and supplementation of female rats with testosterone promoted N-butyl-N-(4-hydroxybutyl) nitrosamine-induced tumor incidence while urothelium targeted AR knockout reduced tumor incidence." (PMID 36720985, 2023). "The AR normally exerts a regulatory role in multiple tissues including muscle, bone, brain, and prostate, but in malignancies this role can be perverted to benefit tumor cell proliferation and survival." (PMID 36720985, 2023). "AR activity also promotes tumor malignancy by regulating invasion and cell migration." (PMID 37894767, 2023). "Additionally, we found that mRNAsi is closely related with serum PSA, androgen receptor (AR), tumor purity, pathological T stage (pT), as well as somatic copy number alterations (SCNAs) and TMB (Remark A)." (PMID 37936202, 2023). "Androgen receptor inhibitors could activate tumor-infiltrating CD8+ T-cells and enhance the efficacy of immunotherapy of RCC in vivo." (PMID 37715192, 2023). "It is more commonly associated with hormone-receptor-positive breast cancer, where AR expression is seen in >70% of tumours, and some small studies have shown AR expression in 30% (n = 13 of 43) of BRCA1mut and 78% (n = 14 of 18) of BRCA2mut tumours." (PMID 36831687, 2023). "Finally, feedforward stabilization of LCMT1 by small molecule activator of phosphatase (SMAP) results in attenuation of AR-signaling and tumor growth inhibition in anti-androgen refractory PCa." (PMID 37644036, 2023). "The same was true for the expression of PR in tumours with nuclear expression of β-catenin (Me [%] = 100) versus without (Me [%] = 45), U = 180.0, p < 0.05 and for expression of AR in tumours with nuclear expression of β-catenin (Me [%] = 30) versus without (Me [%] = 10), U = 163.0, p < 0.05." (PMID 36969079, 2023). "Additionally, the controlled release of both ICG and DOX at acidic tumor conditions due to the dissolution of ZIF‐8 provides a drug‐targeting mechanism in addition to the AR peptide." (PMID 37610511, 2023).
tumor (continued). "Extracted protein from tumor tissues was analyzed for AR and AR-V7 expression via Western blots." (PMID 37046780, 2023). "When formulated with siRNA against the androgen receptor, the Glu-Urea-Lys-LNPs induced enhanced accumulation and cellular internalization at tumor sites, leading to down-regulation of androgen receptor levels and inhibition of tumor cell proliferation in a mouse xenograft model." (PMID 38516300, 2023). "It is clear that LAR-TNBC has a poor pathological complete response (pCR); and anti-androgen therapy (to kill the slow-growing cells) combined with standard chemotherapy drugs, such as paclitaxel (to kill rapidly dividing tumor cells), showed promising results in AR+-TNBC preclinical models." (PMID 36766786, 2023). "The deletion of stromal AR in smooth muscle cells promoted tumor progression in mice." (PMID 36769153, 2023). "The AR tumor suppressor function is usually reversed in androgen depletion-independent (ADI) PC." (PMID 37103355, 2023). "This may indicate that, within the same tumor, cells may use different mechanisms to inactivate AR expression, some being DNA methylation-dependent while others not." (PMID 37892208, 2023). "Additional studies have shown that PARP-1 may additionally have a role in supporting androgen receptor (AR) activity, and that inhibition of PARP-1 activity in vivo may suppress AR function, decrease tumor growth, and delay the onset of castration resistance." (PMID 37168382, 2023). "Indeed, several reports support the superior efficacy of combining inhibitors of the PI3K/AKT/mTOR and AR signaling pathways in reducing tumor growth, both in vitro and in vivo preclinical studies." (PMID 36768610, 2023). "AR is likely involved in tumor progression and related to poor prognosis." (PMID 36614201, 2023). "Amongst the novel BMP4 targets identified were the transcript encoding the dual histone demethylase, KDM7A, previously shown to promote tumour growth and mediate androgen receptor activity, and FGF4; both were upregulated in both cell lines following BMP4 stimulation." (PMID 37048077, 2023). "Considering that besides the MAPK pathway, multiple oncogenic drivers such as EGFR or the androgen receptor promote fatty acid synthesis, the here proposed combinatorial treatment may be applicable to several tumor types." (PMID 37072838, 2023). "Survival analysis showed that AR status and tumor size were independent prognostic factors of PFS." (PMID 36929229, 2023). "More potential LM progression-related markers were detected in CSF samples than in tumor samples, including PREX2 mutation (P = 0.014), IGF1R mutation (P = 0.034), AR mutation (P = 0.038), SMARCB1 deletion (P < 0.001), SMAD4 deletion (P = 0.0034), and TGF-beta pathway aberration (P = 0.0038)." (PMID 37131253, 2023). "Few studies to date have evaluated the prognostic role of AR in residual tumour." (PMID 38273853, 2023). "A recent review highlighted the changes observed in AR signaling in tumor stroma that could influence the tumor’s behavior." (PMID 37686633, 2023). "Here, we demonstrated the tumor-suppressive role of the AR and found that activated AR could directly bind to the regulatory sequence of muscarinic acetylcholine receptor 4 (CHRM4) and downregulate its expression." (PMID 37142586, 2023). "While the AR induction of cellular senescence can be interpreted as a tumor-suppressive phenomenon, the clearance of senescent cells may be desirable, as these cells have the potential to survive indefinitely." (PMID 37190127, 2023). "Moreover, ATAD2 has also been identified as a coactivator of ERα, AR, E2Fs, and c-Myc for the promotion of tumor progression." (PMID 36632213, 2023).
tumor (continued). "In addition, in the case of YCU-SDC-20 with an AR positive primary tumor, we found that the transcription profiles of YCU-SDC-20 and YCU-SDC-20 PDX/YCU-SDC-20X did not correlate well, while those of YCU-SDC-20 PDX and YCU-SDC-20X correlated very well." (PMID 36538240, 2023). "Because the ER is functionally and structurally highly comparable to the AR, responses to AR-targeting drugs may also rely on AR expression in the tumor." (PMID 37568977, 2023). "In addition, tumour volume and tumour/body weight index were statistically significantly increased in the 22Rv1‐si‐AR+FEN1‐OE group as compared with the 22Rv1‐control and 22Rv1‐AR‐KD groups (both p < 0.0001)." (PMID 37326412, 2023). "Subsequently, the AR translocates to the nucleus binds to DNA via the DBD, recruiting various cofactors and ultimately causing the transcription of androgen-dependent genes that drive tumor growth." (PMID 37894395, 2023). "In this sense, it may be possible to resensitize tumor cells to antiandrogens, maintaining or restoring the dependence of the AR signaling axis." (PMID 37189723, 2023). "On the tumor cell level, Ki-67 and AR seem to be fairly robust predictive markers of a pCR." (PMID 36769287, 2023). "AR protein was analyzed in the tumor samples using Western blot." (PMID 37175938, 2023). "Likewise, exosomal miR-92a-2-5p secreted by macrophages boosts the invasiveness of tumour cells by modulating the AR/PHLPP/p-AKT/β-catenin signalling pathway." (PMID 37894344, 2023). "The distribution of AR in cells is closely related to the survival of tumours." (PMID 37431884, 2023). "Still, anti-AR therapy might be suitable in 30% of TNBC patients and detailed tumor tissue RNA expression analysis revealed some TNBC patients (16%) to be classified luminal androgen receptor (LAR) type." (PMID 38001722, 2023). "Interestingly, COMMD3 was significantly associated with markers of luminal differentiation and/or fate commitment in the luminal A-like tumours: tubule formation, androgen receptor (AR), ELF5 and cKIT (Fig-2I)." (PMID 37072858, 2023). "In addition, the DNA-PARP repair pathways are closely connected with the androgen receptor signaling pathway, which is the main regulation pathway for tumor growth in PCa and a therapeutic target for ADT." (PMID 37629155, 2023). "Our results showed that luteolin suppresses tumor proliferation and AR expression." (PMID 37716981, 2023). "Consequently, it can reveal that the tumor with AR + can obtain better clinical results by inhibiting cell proliferation, which is consistent with the results of our survival analysis." (PMID 36929229, 2023). "Despite great benefits and improvements in patients’ survival outcomes, once on ADT the development of mCRPC is just a matter of time and an adaptive mechanism for tumor cells to maintain high intracellular androgen level and overexpress androgen receptor (AR) has been observed in mCRPC." (PMID 38132385, 2023). "BAD upregulation via activated AR may assume a significant relevance, as tumor-suppressor potential has been reported for several BH3-only proteins, consistently with their pro-apoptotic role." (PMID 37686282, 2023). "In addition to AR overexpression and HRAS and PIK3CA-alterations, PD-L1 expression and Tumor Mutational Burden > 10 Mutations per Megabase were identified as additional potentially targetable alterations." (PMID 37427101, 2023). "Similarly, KAT2B (PCAF) is overexpressed in TGCT and potentially promotes tumor progression by acetylating and activating the androgen receptor (AR)." (PMID 37569569, 2023). "Notably, c-Myc overexpression inhibits the transcriptional activity of the androgen receptor (AR), which is the driving force in PCa and the principal therapeutic target in the advanced tumor stage." (PMID 36678591, 2023). "Additionally, combined treatment with AU-15330 and a clinically used AR antagonist (enzalutamide) successfully reduced tumor volume within 3 months." (PMID 37025180, 2023).
tumor (continued). "Therefore, when ADT is performed, the remaining androgens synthesized from adrenal gland and tumor tissues are sufficient to activate androgen receptor." (PMID 36674820, 2023). "Future experiments in vivo are needed in AR+-TNBC mice models to test our hypothesis under more physiological tumor conditions." (PMID 36766786, 2023). "In addition to genetic drivers of PCa, hyperactivity of the androgen receptor, inflammation, TGFβ activity, and DNA damage contribute to tumor progression." (PMID 37095257, 2023). "The mechanistic basis of AR-dependent tumor suppression in ERα-positive malignancies may be due to crosstalk between ERα and AR, where the interaction of the two can inhibit the activity of both." (PMID 37626712, 2023). "Consequently, subsequent increased PARP activity can lead to tumor-cell survival and modulation of AR-axis activity, which in turn can be countered by PARP inhibition." (PMID 36980735, 2023). "Therefore, the intratumoral testosterone synthesis leads to an activation of AR-target genes and maintains tumour cell survival." (PMID 36151426, 2023). "Notably, the combination of JG231 and enzalutamide synergistically inhibited AR/AR-V7 expression and suppressed CWR22Rv1 xenograft tumor growth." (PMID 36773708, 2023). "However, a landmark preclinical study evinced that AR blockade sensitized tumor-bearing mice to PD1 Abs by enhancing the function of cytotoxic CD8+ T-cells." (PMID 37686465, 2023). "Furthermore, a combination of lipogenesis inhibitor (SCD1 INH) and AR antagonist (enzalutamide) was more effective in tumor regression than AR antagonist alone." (PMID 37644825, 2023). "-Boosts invasiveness of tumour cells by modulating AR/PHLPP/p-AKT/β-catenin signalling pathway." (PMID 37894344, 2023). "There may exist subpopulations of Src-dependent CRPC cells or a therapeutic window to co-target AR and Src during the early stage of tumour progression." (PMID 35832549, 2022). "In human PC, even with tumor androgen resistance, cancer cells generally express AR." (PMID 35163087, 2022). "Moreover, PROTAC 12 effectively and completely degraded AR protein in xenograft tumour tissue and was more effective than enzalutamide in achieving tumour growth inhibition in the MDA-MB-453 xenograft model in mice." (PMID 35702041, 2022). "Dilazep, a vasodilator that is used to treat patients with hypertension, cardiovascular, and renovascular disorders, is a second pharmaceutical agent that blocks GATA2 DNA-binding, suppresses the expression of AR, and reduces tumor growth in a murine xenograft model of CRPC." (PMID 36212399, 2022). "Interestingly, the matched primary tumors of MetB cases were generally characterized by relatively high Ki67 and low PSA in primary tumor epithelial cells, and a reactive stroma response with reduced AR-levels in the primary tumor stroma." (PMID 36358614, 2022). "The number of AR appears to correlate with the degree of tumor differentiation." (PMID 35886904, 2022). "AR’s function as a transcription factor and its direct association with gender (a strongly differentiating factor for GBM incidence) suggests its involvement in tumor growth and GBM progression." (PMID 36361793, 2022). "The dependence on BMAL1 as a transcriptional regulator of cellular proliferation may describe the mechanism through which tumor cells evade AR blockades." (PMID 36291899, 2022). "Enzalutamide (tested due to the luminal androgen receptor phenotype), cabozantinib and talazoparib each slowed growth of the tumor compared to vehicle-treated controls but did not cause tumor regression." (PMID 35221336, 2022). "However, a more recent study found that while cytoplasmic AR protein was not significantly different between tumor and adjacent liver tissue, nuclear AR protein levels were significantly elevated in the tumor as compared to adjacent normal liver tissue." (PMID 36430245, 2022). "Except for small cell carcinoma and DNPC, most CRPC tumours express AR proteins." (PMID 35832549, 2022).